HLA-T (major histocompatibility complex, class I, T (pseudogene))
Synonyms: formerly HLA-16
Gene: Unprocessed pseudogene on chromosome 6 (29,896,654 to 29,897,786, forward strand). Ensembl gene ENSG00000231130.
Diseases named in the same sentence as HLA-T in open-access papers:
HLA-T is named in the same sentence as 5 diseases in open-access papers, as found by Europe PMC text mining. Sharing a sentence is not in itself a finding about the gene and the disease. The quoted sentences say what the papers report.
asthma (1 paper, 2024). "Cluster 5, which includes genes at 6p22.1 (HLA-A, HCG4P5, HLA-T, MOG, TRIM26, HCG9, IFITM4P), demonstrated further connections between JIA and a subset of autoimmune/inflammatory traits (i.e., type 1 diabetes, asthma, eczema, and severe COVID-19 or rheumatoid arthritis)." (PMID 39175752, 2024).
HLA-T also shares sentences with these, for which no sentence is quoted: COVID-19 (1 paper); eczema (1); rheumatoid arthritis (1); type 1 diabetes (1).